IL33 (interleukin 33)
Diseases named in the same sentence as IL33 in open-access papers (continued):
Sharing a sentence is not in itself a finding about the gene and the disease.
tumor (continued). "IL-33 signaling can contribute to tumor immunoevasion by promoting Treg cell proliferation." (PMID 37686309, 2023). "Furthermore, the increased IL-33 level in TME or TIME promotes ILC2’s pro-tumor function via binding to its cognate receptor ST2, promoting temporary storage of externally acquired FA in lipid droplets to make cell membranes." (PMID 37275901, 2023). "Moreover, while direct eosinophil-mediated cytotoxicity has been demonstrated in vitro, eosinophil-dependent inhibition of tumor initiation in vivo occurs by IL-33-mediated effects upon CD8+ T cells in the tumor microenvironment." (PMID 37064719, 2023). "In the Proteintech group, IL-33 expression was positively correlated with tumor stage." (PMID 37507682, 2023). "Also, IL-33 exerts tumor supportive action via regulating PPAR-γ-mediated IL-4, IL-13, and IL-15 (Th2 cytokines) release from ILC2s." (PMID 37275901, 2023). "Studies in cancer mouse models revealed that IL-33 from the tumor microenvironment initiates ST2 signaling in Tregs, as well as positively regulating ST2 expression, resulting in enhanced suppressive function, greater AREG production, and increased tumor number and size." (PMID 37197653, 2023). "In the IL-33 serum expression part, the expression level of IL-33 in tumor patients was higher than that in the control group, and the expression level of IL-33 serum was positively correlated with tumor stage and vascular invasion, which was consistent with the result of the IL-33 tissue level." (PMID 37507682, 2023). "Recombinant interleukin-33 (IL-33) inhibits tumor growth, but the detailed immunological mechanism is still unknown." (PMID 37246159, 2023). "The source, location, and concentration of expressed IL-33 and IL-5 levels might explain the reason behind its different tumor-related effects." (PMID 37587450, 2023). "There is also IL-33 immunotherapy and related tumor microenvironment." (PMID 37153553, 2023). "In addition, GM-CSF and IL-33 were also shown to be involved in the regulation of ILC2–eosinophil cross-talk in the tumor microenvironment." (PMID 37508545, 2023). "Moreover, 22 clinical studies assessed IL-33 expression and correlated it with the clinicopathological features of tumors, including tumor size, histological grade, distant metastasis, lymphatic metastasis, and vascular invasion." (PMID 37507682, 2023). "For example, IL-33 was found to increase antigen-specific CD8+ T cell responses and elicit effector-memory CD8+ T cells in a human papillomavirus-associated tumor model; it was therefore considered to be an immunoadjuvant in vaccinations against pathogens, including in antitumor immunotherapy." (PMID 37056569, 2023). "Given the controversial role of IL-33 in promoting tumor cell survival and inducing antitumoral T cell responses, we further stratified CRC tissues into four groups according to IL-33 expression and T cell infiltration: IL-33lowCD3low, IL-33lowCD3high, IL-33highCD3low, and IL-33highCD3high." (PMID 37056569, 2023). "IL-33 is secreted from damaged epithelial cells, activated immune cells, or even tumor cells." (PMID 37587450, 2023). "In addition, CAFs have been found to produce IL-33, which promotes tumor metastasis and immunosuppression through Treg cells." (PMID 37611111, 2023). "Similarly, IL-33 administration increased tumour-infiltrating IL-13+ ILC2s, MDSCs, and Tregs, and correlated with reduced NK cell cytotoxicity and accelerated tumour growth and metastasis to the lung and liver." (PMID 37455828, 2023). "We next examined the surface phenotype changes of the splenic cDC1s from IL-33-treated tumor-free (TF) mice with typical cDC1 markers and found that CD103 expression was markedly enhanced, whereas the other cDC1 markers were minimally affected by recombinant IL-33." (PMID 37246159, 2023). "However, VISTA expression is largely correlated with Il-33 levels in tumor cells and lymphocytes and with PD-L1 in tumor cells." (PMID 36836154, 2023).
tumor (continued). "We found that the additional administration of recombinant murine IL-33 to mice treated with 5-FU led to a more significant delay in tumor growth, prolonged survival, and increased cleaved-caspase 3 than those observed in control mice or mice receiving either rmIL-33 or 5-FU alone." (PMID 37056569, 2023). "Furthermore, IL-33-actived eosinophils have also demonstrated the capacity for direct tumor cell killing via cytotoxic granule release." (PMID 37903733, 2023). "The tumor-promoting role of IL-33 in APC mice might be attributed to the heterogeneity of the TME among different mouse models 36, which will also be further explored." (PMID 37056569, 2023). "In the Abcam group, the expression of IL-33 was positively correlated with tumor stage (OR = 3.478, 95% CI = 2.237–5.407, p < 0.000) and negatively correlated with histological grade (OR = 0.571, 95% CI = 0.372–0.877), p = 0.011) but was not correlated with tumor size or lymphatic metastasis." (PMID 37507682, 2023). "IL-33’s pro-tumor effect in NSCLC was further supported by in vivo research." (PMID 36874133, 2023). "Intratumoral fungi can induce the secretion of IL-33 from tumor cells." (PMID 38169837, 2023). "In the Sigma group, only tumor size was positively correlated with IL-33 expression." (PMID 37507682, 2023). "Moreover, in our study, we have demonstrated that VISTA H-score correlates with Il-33 and PD-L1 levels in tumor cells and Il-33 levels in lymphocytes." (PMID 36836154, 2023). "However, in oncogenesis, IL-33 has been shown to exert dual roles, both inhibitory and stimulatory, on tumor tissue, with the balance likely dependent on the tumor’s immunogenicity, microenvironment, and IL-33 localization." (PMID 37762328, 2023). "Strikingly, PD1d/IL-2v/IL-33 OT1 cells (that is, a 1:1 ratio of PD1d/IL-2v:PD1d/IL-33 cells) induced marked tumor regression and achieved a tumor objective response rate (ORR) of 85.7% (predicted occurrence probability, 83.3%), while the ORR was 0–9% for any other treatment." (PMID 37081150, 2023). "Nevertheless, studies have also shown that IL-33 has anti-tumor properties." (PMID 37686309, 2023). "In addition, immune checkpoint inhibitors (ICIs)—which remove the “brakes” of antitumor immunity—require IL-33 in the tumor to achieve therapeutic efficacy." (PMID 37611111, 2023). "However, in metastatic tumours, where IL-33 content is decreased, the IL-33/ILC2 activation pathways cannot be triggered, and immune evasion is facilitated." (PMID 35557940, 2022). "In short, IL-33 activated ILC2s recruits and amplifies cell response to target tumour cells." (PMID 35557940, 2022). "As such, IL-33-dependent tumour growth in gp130F/F mice correlated with the expansion of mast cell subsets but could not be definitively linked to ILC2, notwithstanding IL-9 (an ‘ILC2-related’ cytokine) as a putative mechanism for MMC expansion in this model." (PMID 35677533, 2022). "IL-33 treatment enhanced tumour burden and correlated with an increase in tumour ST2+ Tregs." (PMID 36263033, 2022). "Taken together, we propose that NFE2L3 promotes CRC through changes in the tumor microenvironment, by suppressing the activity of Tregs and through the activation of mast cells, mediated, at least in part, via the increase of IL33 expression and decrease of RAB pathway signaling." (PMID 35091681, 2022). "However, the tumor microenvironment is complicated, such that not only are molecules such as IL33 present, but so are extreme physical conditions, such as hypoxia." (PMID 36726981, 2022). "Indeed, eosinophils recruited and activated through IL-33 were shown to be responsible for tumor growth control and for the prevention of pulmonary metastases development in melanoma-bearing mice." (PMID 35563461, 2022). "Furthermore, IL33 can enhance proliferation and clonability of HGGs of brainstem origin, while blocking IL33 in brainstem organotypic slice cultures reduced the proliferation of these tumor cells." (PMID 35990702, 2022).
tumor (continued). "Finally, IL‐33 has an ambiguous role preponderant on tumourigenic implications in tumour microenvironments and this implication can be useful to adopt anti‐IL33 therapy." (PMID 35344301, 2022). "Furthermore, IL-33 was recently shown to activate tumor-infiltrated group 2 innate lymphoid cells (ILC2s) to regulate CD8+ T cell responses." (PMID 36256464, 2022). "In support of this, in mouse lung cancer, also IL-33 was related to good prognosis since it could elevate the frequency of tumour infiltrating ILC2s via CCL5, CXCL10, and CXCL12." (PMID 35406451, 2022). "Thus, IL-33 has dual functions in regulating eosinophil-dependent anti-tumor immunity by upregulating CCL11 expression and stimulating eosinophil degranulation." (PMID 35053615, 2022). "IL-33 is an epithelial- and tumor-derived cytokine belonging to the IL-1 cytokine family." (PMID 35563461, 2022). "Our findings support a pivotal role for IL-33 as a gastric (and tumour) epithelium-derived “alarmin” that promotes a protumorigenic immune response, via unidirectional signaling through ST2 receptors on mast cells and via recruitment of immunosuppressive M2 macrophages." (PMID 35677533, 2022). "Of note, IL-33 has been reported to promote a tumor hypoxic microenvironment, with generation of reactive oxygen species, that could lend toward an indirect induction of RBM3 through local hypoxia." (PMID 35908044, 2022). "For PD-1hi anti-tumor TILC2s, IL-33 combined with anti-PD-1 treatment may break through the dilemma of immunotherapy resistance in current clinical practice." (PMID 35720302, 2022). "IL-33 signaling enhances CD8+ T cell activity response to inhibit the tumor growth." (PMID 35634336, 2022). "Notably, administration of a DPP4 inhibitor resulted in higher concentrations of the chemokines CCL11, interleukin (IL)-4, IL-5, and IL-33 in tumor extracts and increased migration of eosinophils into solid tumors." (PMID 35053615, 2022). "Whether differential IL-33 expression during the stages of tumour progression affect downstream mast cell function, and whether mast cells directly contribute to the tumour-modulatory effects of IL-33 in CRC remains to be established." (PMID 36263033, 2022). "Next, we assessed whether macrophages might contribute to the elevated Il33 expression in gp130F/F tumour, or if they might be recruited to tumour sites via IL-33 signaling." (PMID 35677533, 2022). "Moreover, immunohistochemical analysis of tumor tissue samples from a large number of CRC patients showed that the upregulation of IL-33/ST2 was significantly correlated with an early tumor stage, but not with the prognosis of patients." (PMID 35720302, 2022). "In mice, the majority of tumor ILC2s are regulated by IL-33/ST2." (PMID 35720302, 2022). "IL-33 thus provides a selective pressure for ST2L-negative cells that might expand into regions adjacent to the tumor blood vessels following hypoxia-inducible factor 1 (HIF-1)-dependent translocation, thereby increasing the proportion of the malignant cells." (PMID 35634336, 2022). "Conversely, others have found that IL-33 may instead inhibit metastasis through inducing CD40L expression on tumour infiltrating lymphocytes." (PMID 36263033, 2022). "In addition, studies have also shown that IL-33 level in tumor tissues of patients with NSCLC is significantly lower than that in adjacent tissues." (PMID 35634336, 2022). "Then, the IL-33-stimulated TAMs promote the intravasation process of the tumor cells." (PMID 36499246, 2022). "Angiogenesis blockers have proved beneficial clinically against CRC, and combined treatment through the inhibition of IL-25 or IL-33 may provide additional benefits to further reduce tumour angiogenesis." (PMID 36263033, 2022). "This suggests that IL-33 and its effector cells may play a more important role in tumorigenesis, compared with tumor progression." (PMID 35720302, 2022).
tumor (continued). "Furthermore, IL-33 affects the tumor microenvironment (TME) through immune cells, such as myeloid-derived suppressor cells (MDSCs), dendritic cells (DCs), and regulatory T cells (Tregs)." (PMID 35409061, 2022). "Similar conditions are possible in some tumor lesions where high IL-33 expression may potentiate an activation state in basophils." (PMID 35159247, 2022). "In addition to its direct effect on the tumor cells, promoting their proliferation and tumor growth, IL-33 is involved in the TME to promote angiogenesis, matrix remodeling, and cytokines and growth factors produced by the TME components." (PMID 36499246, 2022). "For IL-33/ST2-regulated pro-tumor TILC2s, sST2 may also be a good choice in addition to traditional antibodies." (PMID 35720302, 2022). "Additionally, IL-33 induced by GBM tumor cells is another important inflammatory mediator that accelerates GBM proliferation, migration, and invasion." (PMID 35572545, 2022). "Inflammatory proteases from neutrophils (proteinase 3, elastase, and cathepsin G) and mast cells within the tumor microenvironment (chymase, tryptase, and granzyme B) can process full-length IL-33 into shorter mature forms (18–21 kDa), with a 10- to 30-fold higher amount of activity." (PMID 35409061, 2022). "Both IL-25 and IL-33 have been shown to promote CRC tumour cell stemness." (PMID 36263033, 2022). "Notably, ligand/receptor pairs such as Il33/Il1rl1 (St2) and Cxcl12/Cxcr4 not only were abundant in tumors but also detected in cultured tumor cells." (PMID 35902768, 2022). "Interrupting the PD-1 signaling pathway that activates tumor-infiltrating ILC2s can promote antitumor effects, and a combination of IL-33 treatment and anti-PD-1 therapy may maximally expand ILC2s and promote their function." (PMID 35409105, 2022). "A variety of tumor-promoting effects of IL-33 have been found in previous studies." (PMID 36110250, 2022). "Additionally, this group demonstrated that tumor cell expression of the alarmin IL-33 was necessary and sufficient for eosinophil-mediated anti-tumor responses and that this mechanism enhanced the efficacy of immune checkpoint inhibitors." (PMID 35053615, 2022). "Accordingly, inhibition of the epidermal growth factor receptor (EGFR) via gefitinib in AOM/DSS mice led to decreased tumour burden, and this correlated with a reduction in intestinal epithelial cell Il33 expression which the authors attributed to for the pro-tumoral effect of EGFR signalling." (PMID 36263033, 2022). "IL-33 production driven by these cytokines is thought to be responsible for the pro-tumor activity of these immune cells, leading to increased angiogenesis and tumor metastases." (PMID 35203256, 2022). "Recent studies have revealed that IL-33 could play a dual role in bone metastasis of PCa through regulating the immune surveillance and the progression of tumor." (PMID 36237303, 2022). "The expression of IL-33 was high in normal tissues but low in parts of tumor samples." (PMID 35382168, 2022). "Another study found that PDAC tumor cells releasing IL-33 depended on the intratumoral fungal mycobiome, and genetic deletion of IL-33 or anti-fungal treatment in murine PDAC could reduce Th2 and ILC2 recruitment and improve survival." (PMID 35720302, 2022). "Studies in APC-mutant mice found that decreased tumour burden upon IL-33-deficiency (but not IL-25-deficiency) is associated with reduced tumour mast cells, suggesting a potential pro-tumoral role downstream IL-33 signalling." (PMID 36263033, 2022). "Studies in the past decade have begun to uncover the important roles of IL-25 and IL-33 in shaping the CRC tumour immune microenvironment, where they may promote or inhibit tumorigenesis depending on the specific CRC subtype." (PMID 36263033, 2022).
tumor (continued). "Based on its pro-tumor and anti-tumor functions, in humans, IL33 is correlated with poor prognosis in glioma and hepatocellular carcinoma (W. Wang, Wu, Ji, & Wu, 2020; J. Zhang, Wang, Ji, Ding, & Lu, 2017) while it is associated with better prognosis in lung cancer and colorectal cancer." (PMID 35122833, 2022). "A9 appearance greatly reduces IL-33 prevalence and increases circulating tumour cells (CTCs)." (PMID 35557940, 2022). "The anti-tumor effects of IL-33 were completely abrogated by the depletion of eosinophils." (PMID 34209038, 2021). "A better understanding of the mechanisms of the complex communication network of the TME via IL-33 in tumor–stromal signaling, on a cellular and molecular basis, may provide a new potential therapeutic target for the treatment of HNSCCs." (PMID 34298657, 2021). "Integration of ATAC-seq and RNA-seq data showed that FAK-dependent chromatin accessibility is linked to differential gene expression, including of the FAK-regulated cytokine and transcriptional regulator interleukin-33 (Il33), which controls anti-tumor immunity." (PMID 33420223, 2021). "Elevated IL‐33 levels in ESCC are related to the invasion of Treg cells in the tumour." (PMID 33305406, 2021). "Current studies have found that up-regulation of IL-33 in HCC leads to accelerated growth of HCC, and IL-33 may induce chemokines (such as Cxcl1) to enhance the recruitment of S100A9-secreting bone marrow cells to promote tumor progression." (PMID 35096588, 2021). "Thus, targeting the IL-33-enhanced-CXCR4 regulatory circuit attenuates tumor aggressiveness and provides a potential therapeutic option for improving the prognosis in HNSCC patients." (PMID 34298657, 2021). "Accordingly, tumor PCs have distinct effects on tumor-associated macrophages (TAMs) in TME, while IL-33 produced by PDGF-BB-stimulated PCs has been shown to recruit TAMs in order to promote cancer metastasis in several human and mouse xenograft models (process ➀)." (PMID 34179005, 2021). "In human basophils, IL-33, in synergy with IL-3, stimulates IL-9 production, which may strengthen tumor immunity." (PMID 34209038, 2021). "Likewise, IL-33-activated NK cells producing IFN-γ contribute to anti-tumor immunity by direct killing of tumor cells." (PMID 34209038, 2021). "However, despite expression of secreted IL33 in these tumors, tumor ultimately progressed rapidly in control mice." (PMID 33553191, 2021). "IL11 may trigger tumor cells to release IL33, potentially shifting it from an alarmin to an actively secreted product." (PMID 34235145, 2021). "The mechanism of the effect of IL33 on tumor progression is still controversial." (PMID 35011007, 2021). "Furthermore, inhibition of DPP4 reveals IL-33-dependent eosinophil-mediated control of tumor growth." (PMID 33614513, 2021). "So, in some cases, eosinophil degranulation infiltrating the tumor is crucial to tumor rejection and activation of CD8 T cells and consequent tumor killing; alternatively, eosinophils may participate directly in tumor killing after activation by IL-33." (PMID 34209213, 2021). "IL-33 expression was rarely observed and had no prognostic significance but its expression on TCs was significantly associated with tumor location." (PMID 34572318, 2021). "Furthermore, overexpression of IL-33 in B16 and 4T1 tumor cells inhibited tumor growth, correlating to increased tumor infiltration of IFN-γ+ NK cells." (PMID 34209038, 2021). "Despite strong antitumor efficacy, the genetic mechanism underlying CD8+ T cell-mediated immune responses in the IL33-impinged tumor microenvironment (TME) has not been explored." (PMID 33553191, 2021). "Similarly, tumour growth was markedly reduced following IL-33 treatment, which was attributed to an increase in the migration and viability of cytotoxic eosinophils in a model for colorectal cancer." (PMID 33401460, 2021).